IBSP (integrin binding sialoprotein)
Diseases named in the same sentence as IBSP in open-access papers (continued):
Sharing a sentence is not in itself a finding about the gene and the disease.
osteosarcoma (15 papers, 2003 to 2026). A usually aggressive malignant bone-forming mesenchymal neoplasm, predominantly affecting adolescents and young adults. "Further analysis of the data also revealed that higher IBSP expression was significantly associated with poor overall survival and relapse-free survival in osteosarcoma patients." (PMID 38006395, 2023). "The univariate and multivariate Cox analysis confirmed that IBSP expression was an independent risk factor (HR = 3.377, 95% CI: 1.775-6.424, P < 0.001) for relapse free survival in osteosarcoma patients." (PMID 38006395, 2023). "IBSP expression exhibited satisfied diagnostic ability for osteosarcoma with AUC of 1.000 and cut-off value of −2.331." (PMID 38006395, 2023). "The univariate and multivariate Cox analysis confirmed that IBSP expression was an independent risk factor (HR = 3.425, 95% CI: 1.604–7.313, P = 0.002) for overall survival in osteosarcoma patients." (PMID 38006395, 2023). "IBSP expression exhibited satisfied diagnostic ability for osteosarcoma." (PMID 38006395, 2023). "To investigate the impact of IBSP on tumor progression, we first compared the expression levels of IBSP between osteosarcoma cell lines (143B, Saos2) and normal osteoblast cells (hFOB1.19) using RT-qPCR assay." (PMID 38755647, 2024). "Subsequently, we conducted immunohistochemical staining, confirming the expression of IBSP in osteosarcoma tissues." (PMID 38755647, 2024). "The role of IBSP on the progression of osteosarcoma was investigated to provide new targets for the treatment of osteosarcoma." (PMID 38006395, 2023). "Based on this aim, this study screened out the IBSP as a promising biomarker for diagnosis and prognosis prediction for osteosarcoma." (PMID 38006395, 2023). "IBSP has also been shown to play a role in tumorigenesis and metastasis in multiple types of cancer, including osteosarcoma." (PMID 38006395, 2023). "The mRNA expression of IBSP was higher in osteosarcoma than normal tissue with P-value less than 0.0001." (PMID 38006395, 2023). "Our analysis revealed that IBSP expression is significantly higher in osteosarcoma tumor tissues compared to normal bone tissues." (PMID 38006395, 2023). "Further research is necessary to elucidate the specific role of IBSP in osteosarcoma progression and the design of targeted therapies to inhibit IBSP signaling in high-risk patients." (PMID 38006395, 2023). "The results indicated that, compared to the NC group, the volume and weight of tumors in the oe-IBSP group significantly increased, suggesting that IBSP may promote the proliferation of osteosarcoma cells." (PMID 38755647, 2024). "Moreover, we discovered and validated the role of a new signaling axis, ETS2/IBSP, in LN metastasis of osteosarcoma." (PMID 38755647, 2024). "In brief, we identified and verified the key role of ETS2/IBSP, a new signaling axis, in LN metastasis in osteosarcoma, which could provide new targets and direction to block metastasis." (PMID 38755647, 2024). "While the exact mechanism and specific signaling pathways by which IBSP promotes osteosarcoma progression remains unclear, it is thought that IBSP enhances cell adhesion and migration, promoting the invasion and metastasis of cancer cells in bone tissue." (PMID 38006395, 2023). "IBSP could serve as a potential biomarker for osteosarcoma, which could aid in early detection and disease monitoring." (PMID 38006395, 2023). "The higher IBSP expression was observed in osteosarcoma (P < 0.001), confirmed by the IHC staining." (PMID 38006395, 2023). "The univariate and multivariate analysis confirmed that IBSP expression was an independent risk factor for OS (HR = 3.425, 95% CI: 1.604–7.313, P = 0.002) and RFS (HR = 3.377, 95% CI: 1.775–6.424, P < 0.001) in osteosarcoma patients." (PMID 38006395, 2023). "Furthermore, higher IBSP expression is significantly correlated with poor overall and relapse-free survival in osteosarcoma patients." (PMID 38006395, 2023).
osteosarcoma (continued). "The IBSP expression was higher in osteosarcoma cells (P < 0.05)." (PMID 38006395, 2023). "Finally, our bioinformatic analysis of osteosarcoma revealed that IBSP expression is significantly higher in tumor tissues compared to normal bone tissues." (PMID 38006395, 2023). "However, the role of IBSP in mediating invasion and metastasis in osteosarcoma is still unclear." (PMID 38755647, 2024). "In the high TELscore group, LRP1, ITGB1, IBSP, COL1A1, and COL1A2 were the most active signaling pathways of others in osteosarcoma cells." (PMID 39980969, 2024). "Subsequently, we performed silence and overexpression functional experiments of IBSP and ETS2 in the osteosarcoma cell lines." (PMID 38755647, 2024). "The IBSP expression was evaluated in normal cell lines including HaCaT and HOB (Human Osteoblasts), and osteosarcoma cells including SaOS2, U2-OS, and MG-63." (PMID 38006395, 2023). "By the way, CD117, IBSP (Stro-1), ID1, SOX9, CD24, CD44 and THBS-1 were also reported to affect osteosarcoma growth and stemness." (PMID 34828292, 2021). "By conducting knockdown experiments in SAOS-2 cells, we here showed that MEF2C drives IBSP expression in line with reports in mouse MC3T3 cells and its pro-osteogenic role in this human osteosarcoma cell line." (PMID 32195247, 2020). "It is perhaps not surprising when considering the role IBSP plays in the development of osteosarcoma." (PMID 38006395, 2023). "In this bioinformatic analysis of osteosarcoma, we obtained the data of IBSP expression and clinical characteristics from the publicly available cancer genome database TARGET and examined the expression levels of IBSP in tumor samples." (PMID 38006395, 2023). "However, the role of IBSP as a biomarker in osteosarcoma progression has not been studied yet." (PMID 38006395, 2023). "However, the function of IBSP in osteosarcoma has not been studied yet." (PMID 38006395, 2023).
bone metastasis (7 papers, 2012 to 2025). Transfer of a neoplasm from its primary site to bones. "RNA sequencing implied that IBSP expression was markedly higher in bone metastasis samples." (PMID 39118232, 2024). "Nonetheless, miR-19a or IBSP alone did not increase the incidence of bone metastasis." (PMID 34465793, 2021).
glioma (7 papers, 2012 to 2026). A benign or malignant brain and spinal cord tumor that arises from glial cells (astrocytes, oligodendrocytes, ependymal cells). "Furthermore, although not correlating to response to irradiation, recent studies have shown that COL1A1, ITGA7, ITGB3, ITGB4, HMMR and IBSP upregulation confer low survival rate to glioma patients." (PMID 34211843, 2021). "In comparison to other glioma subtypes, the GS2 exhibited higher expression levels of IBSP, PLA2G2A, NNMT, CA9, and MMP9, while the GS5 showed higher expression levels of CHI3L1, IGFBP2, EMILIN3, MEOX2, and PDPN." (PMID 38332637, 2024). "The results indicated that IBSP, MEOX2, and EPHB1 were inclined to express highly in glioma tissues compared with the adjacent relatively normal tissues, while the expression of NOG and GFRA1 tended to decrease in glioma tissues." (PMID 37501725, 2023).
osteoporosis (7 papers, 2021 to 2026). A condition of reduced bone mass, with decreased cortical thickness and a decrease in the number and size of the trabeculae of cancellous bone (but normal chemical composition), resulting in increased fracture incidence. "Then, six hub genes (COL1A1, IBSP, CTSD, RAC2, MAF, and THBS1) were obtained through the integration of multisource databases and they were all significantly upregulated in both the osteoporosis and atherosclerosis group compared with the control group." (PMID 35937806, 2022).
esophageal squamous cell carcinoma (5 papers, 2019 to 2024). Esophageal squamous cell carcinoma (ESCC) is a type of esophageal carcinoma (EC) that can affect any part of the esophagus, but is usually located in the upper or middle third. "IBSP overexpression is significantly related to lymph node metastasis in esophageal squamous cell carcinoma." (PMID 34503278, 2021). "For instance, IBSP is highly expressed in esophageal squamous cell carcinoma (ESCC) tissues." (PMID 34976784, 2021).
multiple myeloma (5 papers, 2001 to 2026). "IBSP was found to be expressed by all osteotropic cancers examined, including prostate, lung, thyroid, neuroblastoma, and multiple myeloma; thus, this bone matrix protein might be implicated in the preferential seed and growth of metastatic cells in bone." (PMID 33514011, 2021). "Furthermore, we validated differentially methylated genes with osteogenic roles in the myeloma context, including RUNX2 and IBSP." (PMID 33462210, 2021).
lymph node metastasis (4 papers, 2019 to 2021). "Significant association was observed between the mRNA expression of IBSP with the CRC tumor grade and lymph node metastasis (p < 0.05)." (PMID 33987980, 2021). "Up-regulation of IBSP is positively correlated with lymph node metastasis, TNM stage as well as poor clinical outcomes for ESCC patients." (PMID 34976784, 2021). "The TMA results demonstrated that the upregulation of IBSP protein expression has a significant relationship with lymph node metastasis, and the effect of IBSP on cell migration was studied by migration experiments." (PMID 31709184, 2019).
melanoma (3 papers, 2020 to 2026). A malignant, usually aggressive tumor composed of atypical, neoplastic melanocytes. "We then tested RUNT domain influence in driving melanoma cell migration to the bone by analyzing the expression of IBSP and SPP1 genes." (PMID 32204402, 2020). "In RUNT KO melanoma cells, reduced expression of genes involved in metastatic processes (e.g., CD31, MMP9 and VEGFA) was observed, and genes involved in promoting bone metastasis, such as IBSP (coding for bone sialoprotein) and SPP1 (coding for osteopontin), were downregulated." (PMID 32204402, 2020).
diabetes (2 papers, 2018 to 2024). "No change was observed in mRNA expressions of IBSP and OCN at bone–implant sites of the rats in control, diabetes, and diabetes + MF groups." (PMID 39202505, 2024).
dystocia (2 papers, 2013 to 2025). Slow or difficult obstetric labor or childbirth. "IBSP and MEPE were identified as possible candidates for protein and fat percentage in Israeli Holstein, but have also been associated with bone formation in humans and declared as candidate genes for dystocia and stillbirth in Norwegian Red cattle." (PMID 24359457, 2013).
malignant glioma (2 papers, 2012 to 2022). A grade III or grade IV glioma arising from the central nervous system. "Of the 12 overexpressed genes, ABCC3, COL8A1, IBSP and PDPN are reportedly associated with GBM, while CTHRC1, PDLIM4 and MYL9 are associated with high-grade and malignant gliomas, respectively." (PMID 35456975, 2022).
metastasis (2 papers, 2022). The spread or migration of cancer cells from one part of the body (where they first appeared) to another. "Moreover, we have validated some previously reported overexpressed genes such as TGFB1, IBSP, MMP9, or ITGB3 in bone metastasis; CRYAB, NRCAM, and SOX2 in brain metastasis; VEGF and IL6 in lung metastasis; and CYP4F3 in liver metastasis." (PMID 34051058, 2022).
brain tumors (1 paper, 2023). "Moreover, in brain tumors, ITGB8 and ITGAV integrins show the highest expression in primary proneural and mesenchymal gliomasphere cultures, while their interaction with the integrin-binding syalo-protein IBSP promote tumor cell migration." (PMID 37835469, 2023).
Follicular Cyst (1 paper, 2023). Cyst due to the occlusion of the duct of a follicle or small gland. "We compared transcriptomic data from follicular cysts to the reference genome and identified non-synonymous mutations in three genes: IBSP, LDHB and PRLR." (PMID 38274662, 2023). "These genes are involved in several pathways involved in follicular cyst formation: ECM-receptor interaction (IBSP), PI3K-Akt signaling pathway (IBSP and PRLR) and metabolic pathways (LDHB)." (PMID 38274662, 2023).
laryngeal carcinoma (1 paper, 2021). Carcinoma that arises from the laryngeal epithelium. "Among them, RCN1 (hazard ratio (HR): 1.928852, 95% confidence interval (CI): 1.194018-3.115926, p-value = 0.007261) and IBSP (HR: 1.928852, 95% CI: 1.194018-3.115926, p-value = 0.007261) were risk factors for laryngeal cancer." (PMID 34976784, 2021). "RCN1, DNAJA2, LASP1 and IBSP were up-regulated in laryngeal cancer." (PMID 34976784, 2021). "Our data confirmed that RCN1, DNAJA2, LASP1 and IBSP were up-regulated while LAT2, FUZ, HOOK2 and DAPK2 were down-regulated in laryngeal cancer." (PMID 34976784, 2021).
mental disorder (1 paper, 2024). A disease that has its basis in the disruption of mental process. "Our study suggested that IBSP could be a potential site for regulating renal function and mental disorders." (PMID 38858783, 2024).
postmenopausal osteoporosis (1 paper, 2015). Metabolic disorder associated with fractures of the femoral neck, vertebrae, and distal forearm. "Two significant SNPs within IBSP, rs1054627 and rs17013181, were associated with BMD and postmenopausal osteoporosis by the two-stage strategy, and rs17013181 was also significantly associated with serum IBSP levels." (PMID 26568273, 2015). "Two SNPs in IBSP, rs1054627 and rs17013181, may confer risk of postmenopausal osteoporosis in Han Chinese women, and be useful in the informative assessment of the genetic risk for reduced BMD together with serum IBSP level." (PMID 26568273, 2015).
viral infection (1 paper, 2023). "For the first time, we have identified new CRS-related genes such as ADGRG7, probably reflecting cellular-adhesion elements, LACRT, IBSP, MEPE, and IFITM5, probable antimicrobial genes with a potential role in viral infections." (PMID 36982612, 2023). "Our study has shown upregulated bone-homeostasis genes—human bone sialoprotein gene IBSP (generally upregulated), extracellular phospoglycoprotein MEPE, and interferon-induced transmembrane protein 5 IFITM5 (both upregulated only in CRSsNP), which may play a potential role in viral infection." (PMID 36982612, 2023).
tumor (61 papers, 2001 to 2026). "Integrin‐Binding Sialoprotein (IBSP) has been implicated in tumor progression across various cancers." (PMID 39118232, 2024). "IBSP, an osteoblast differentiation marker, is associated with osteoblastogenesis, bone formation and tumor-induced osteolysis." (PMID 30918839, 2019). "The results showed that IBSP upregulation was an independent risk factor affecting the overall survival of patients (P = 0.002), tumor cell differentiation (P = 0.001), and TNM stage (P = 0.001)." (PMID 31709184, 2019). "The IBSP gene encodes bone sialoprotein, which is involved in cell adhesion and migration and may be related to tumor metastasis." (PMID 38755647, 2024). "Loss of IBSP also preserved the density of tumor-bearing bones." (PMID 34465793, 2021). "IBSP facilitates the anchorage and colonization of disseminated tumor cells (DTCs) within the mineralized bone matrix, reinforcing the vicious cycle of tumor-induced bone destruction." (PMID 41596432, 2026). "New evidence shows that IBSP is involved in the progress of tumors, including accelerate matrix breakdown and promote tumor invasion." (PMID 39118232, 2024). "In vivo experiments also confirmed that overexpressing IBSP promoted tumor growth and lymph node metastasis in mice." (PMID 38755647, 2024). "Silencing IBSP (si‐IBSP) mitigated the effects of SMAD4‐induced tumor proliferation, confirming that IBSP acts as a downstream target of SMAD4 in the BMP signaling pathway." (PMID 39118232, 2024). "We revealed that upstream transcription factor SMAD4 enhances the translation of downstream IBSP that can promote tumor migration and invasion." (PMID 39118232, 2024). "Studies have shown that IBSP plays a significant role in tumor growth, invasion, and metastasis by promoting angiogenesis, cell migration and adhesion, and immune microenvironment." (PMID 38006395, 2023). "Integrin-binding sialoprotein (IBSP) isolated from the transcriptome analysis was put forward as a mediator of tumor cell migration." (PMID 37174724, 2023). "We also quantified the total area of TRAP + OC surface and its percentage of total bone surface area (OC.S/BS%) in the tumor-bearing bones and found that synchronous overexpression of miR-19a and IBSP significantly increased the osteoclastogenesis." (PMID 34465793, 2021). "We also detected the expression of IBSP, Fyn, and β‐catenin in tumor and non‐carcinoma tissues of 14 patients and calculated their correlation." (PMID 33987980, 2021). "Results from TRAP staining of the tumor-bearing tibias also suggested that the IBSP knockout led to decreased osteoclastogenesis." (PMID 34465793, 2021). "We obtained consistent results in clinical specimens, compared with adjacent non‐tumor tissues, and the IBSP mRNA and protein levels evidently increased in primary CRC tissue samples." (PMID 33987980, 2021). "We found that the injection of miR-19a-containing exosomes and IBSP significantly promoted tumor growth in the bones, which resulted in a decrease in bone density and an increase in OC activity." (PMID 34465793, 2021). "We found that ectopic expression of both IBSP/miR-19a resulted in a significant decrease in bone density in the tumor lesions." (PMID 34465793, 2021). "Tumor cells express integrin αvβ3 and integrin αvβ5, which can specifically interact with osteopontin and integrin-binding sialoprotein (IBSP), respectively, leading to cancer cell colonization in the bone marrow." (PMID 31753020, 2019). "KM analysis indicated that the overall survival rate of ESCC patients decreased with the upregulation of IBSP in tumor tissues." (PMID 31709184, 2019). "In summary, the results of this study showed that IBSP upregulation was often found in ESCC tumor specimens, indicating the poor prognosis of ESCC patients." (PMID 31709184, 2019). "The mean level of IBSP expression was markedly higher in ESCC tumor tissues than in their non-tumor counterparts (9.95 vs. 3.59, P < 0.001, paired Student's t-test)." (PMID 31709184, 2019).